MBL2 (mannose binding lectin 2)
Diseases named in the same sentence as MBL2 in open-access papers (continued):
Sharing a sentence is not in itself a finding about the gene and the disease.
tuberculosis (21 papers, 2011 to 2025). A chronic, recurrent infection caused by the bacterium Mycobacterium tuberculosis. "Low levels of MBL-2 have been associated with protection against tuberculosis while others have reported its association with tuberculosis susceptibility." (PMID 26693353, 2015). "Variations in MBL-2 gene influences tuberculosis susceptibility and the reports of MBL-2 gene involvement have been contradictory." (PMID 26693353, 2015). "Mannose-binding lectin 2 promoter polymorphisms and structural variants have been associated with susceptibility to tuberculosis." (PMID 23304495, 2012). "MBL2 genotype associations of all TB cases, cases infected with M. tuberculosis and cases infected with M. africanum, compared with controls." (PMID 21695215, 2011). "The CD and CRPS patients were found to have heterozygous mutations in MBL2 and DDX58, mutations that have been associated with susceptibility to tuberculosis." (PMID 31249631, 2019). "The study needs to be validated in larger samples to get a clearer picture of frequency distribution of MBL-2 and VDR genetic variants and their association to tuberculosis susceptibility in different parts of India." (PMID 26693353, 2015). "Genetic polymorphism in Mannose Binding Lectin-2 (MBL-2), a central player in the innate immune response and Vitamin D Receptor (VDR), an immunomodulator has been found to influence the susceptibility to tuberculosis." (PMID 26693353, 2015). "Genetic polymorphism in Mannose Binding Lectin-2 (MBL-2) and Vitamin D Receptor (VDR) is known to influence the susceptibility to tuberculosis." (PMID 26693353, 2015). "The present study involved the frequency distribution analyses of MBL-2 and VDR polymorphisms, two molecules known to play a key role in tuberculosis susceptibility." (PMID 26693353, 2015). "Mannose-binding lectin (MBL2) is considered to play a role in the human innate immune response to tuberculosis (TB) infections, and 4 common single nucleotide polymorphisms (SNPs) may be associated with pulmonary tuberculosis (PTB) risk." (PMID 32746927, 2020). "In addition, the CD and CRPS patients were found to have heterozygous mutations in MBL2 and DDX58, mutations that have been associated with susceptibility to tuberculosis." (PMID 31249631, 2019). "MBL2 variants, either structural alleles (codons 54) in Gambian children and South African adults, or full promoter haplotypes responsible for low MBL production, have been shown to be protective against tuberculosis." (PMID 28540182, 2017). "In the near future, because of the significant public health impact of TB, definite concept, role, and mechanism of MBL2 gene in during infection and replication of M. tuberculosis studies are warranted." (PMID 27876780, 2016). "However, contradictory results among different populations have been reported, resulting in no convincing evidence of association between mannose-binding lectin 2 and susceptibility to tuberculosis." (PMID 23304495, 2012). "First, the variant G57E of the mannose-binding Lectin (Protein C) 2 (MBL2) gene was associated with TB caused by M. africanum, but not by M. tuberculosis sensu stricto." (PMID 29375571, 2017). "Of identified core proteins, complement factor H formed a diagnostic classifier that distinguished latent Mtb infection from healthy controls with good performance, and we also identified C4B, MBL2, SAA1, and matrix Gla protein as potential proteomic signatures of active tuberculosis." (PMID 40736242, 2025). "Several studies have shown MBL2 SNPs of promoter and exonic region regulate the MBL2 serum levels in different autoimmune diseases and infectious diseases, including HIV infection, leishmaniasis, leprosy, malaria, schistosomiasis, tuberculosis and trypanosomiasis." (PMID 27390651, 2016).
autoimmune disease (14 papers, 2005 to 2023). A disorder resulting from loss of function or tissue destruction of an organ or multiple organs, arising from humoral or cellular immune responses of the individual to their own tissue constituents. "Although MBL2-related studies have mostly focused on infectious and autoimmune diseases, studies have increasingly shown that MBL2 gene polymorphisms are implicated in the risk and prognosis of different types of tumors." (PMID 37835594, 2023). "Mannose-binding lectin (MBL) deficiency caused by the variability in the MBL2 gene is responsible for the susceptibility to and severity of various infectious and autoimmune diseases." (PMID 33668563, 2021). "The innate immune complement protein Mannose binding lectin (MBL) and their MBL2 genetic variants are associated with different infectious and autoimmune diseases." (PMID 24751721, 2014).
leprosy (13 papers, 2011 to 2024). Leprosy is a chronic infectious disease affecting primarily the skin and peripheral nervous system. "Research has shown that polymorphisms in the exons and promoter region of the MBL2 gene confer susceptibility to leprosy in Brazil." (PMID 38440733, 2024). "Haplotypic frequencies of MBL2 exon 1 polymorphisms in multibacillary (MB) and paucibacillary (PB) leprosy patients within gender." (PMID 33013845, 2020). "In 2007, the association between MBL2 and leprosy was revealed by a study examining polymorphisms at the promoter and exon 1 regions of this gene." (PMID 32373110, 2020). "In summary, our data suggest that MBL2 exon 1 polymorphisms are associated with an increased risk to leprosy development and progression." (PMID 33013845, 2020). "In this population, the B variant of MBL2 exon 1 polymorphism was associated with susceptibility in leprosy patients for progression to MB form." (PMID 33013845, 2020). "Genotypic frequency of MBL2 exon 1 polymorphisms, analyzed by grouped genotypes, between female MB and PB leprosy patients." (PMID 33013845, 2020). "Genotypic frequency for B variant (rs1800450), located at codon 54 of exon 1 of MBL2 gene, among multibacillary (MB) and paucibacillary (PB) leprosy patients." (PMID 33013845, 2020). "These two findings were subsequently confirmed by a candidate loci association study using Han Chinese, in which the authors found that genetic variants of FCN2 and MBL2 genes conferred susceptibility to leprosy." (PMID 32373110, 2020). "Our findings indicate MBL2 exon 1 polymorphisms to be associated to a reduction in serum protein concentration as a risk for the development of leprosy, especially in the MB form." (PMID 33013845, 2020). "Genotype and allele frequency distributions for MBL2 exon 1 polymorphisms in leprosy per se, paucibacillary (PB) and multibacillary (MB) patients and controls." (PMID 33013845, 2020). "Genotypic frequency of MBL2 exon 1 polymorphisms, analyzed by grouped genotypes, between female leprosy patients and female controls." (PMID 33013845, 2020). "The LYPA haplotype of MBL2 was associated with susceptibility to leprosy per se and to progression to the lepromatous and borderline forms of the disease in subjects from southern Brazil." (PMID 22220182, 2011). "Haplotypic frequencies of MBL2 exon 1 polymorphisms in leprosy patients and controls within gender." (PMID 33013845, 2020). "MBL2 polymorphisms have been associated with several infectious diseases, including leprosy." (PMID 33013845, 2020). "The MBL2 variants have been associated with various diseases, including leprosy." (PMID 33013845, 2020). "We verify the influence of MBL2 exon 1 polymorphisms on leprosy immunopathogenesis." (PMID 33013845, 2020). "Moreover, the B variant of MBL2 exon 1 polymorphism was associated with susceptibility in leprosy patients for progression to MB." (PMID 33013845, 2020). "Since the first suggestion of balancing selection operating on the polymorphism of the gene encoding mannose-binding lectin (MBL2) due to protection against leprosy, much has been done investigating the possible roles played by LP genes and their products on the susceptibility to this disease." (PMID 32240160, 2020). "However, very scanty data is available regarding role of rs11003123, rs36014597, rs7084554, rs11003124 SNPs of MBL2 gene only a single study had shown the association of rs11003124 with leprosy in Han Chinese population." (PMID 27390651, 2016). "Indeed, several polymorphisms of genes of the complement system are associated with leprosy: mannose-binding lectin (MBL2), ficolins (FCN1, FCN2 and FCN3), the serine protease associated with them (MASP2—mannose-binding lectin serine protease 2) and complement receptor 1 (CR1, also known as CD35)." (PMID 30092084, 2018). "Another GWAS study has confirmed the association of complement genes FCN2, MBL2, and CFH with leprosy susceptibility." (PMID 38440733, 2024).
leprosy (continued). "A recent study investigated MBL2 gene polymorphism and serum MBL levels in patients with leprosy, demonstrating that age can influence the MBL2 phenotype." (PMID 35622698, 2022). "Summary of associations between genes of innate immune response MBL2, VDR, NRAMP1, MRC1, and leprosy." (PMID 26793196, 2015). "Mannose-binding lectin (MBL), with its polymorphisms in MBL2, is an example of an acute-phase protein involved with the activation of the complement system by the lectin pathway, which has been extensively investigated in leprosy." (PMID 38053036, 2023). "Therefore, the aim of this study was to evaluate the influence of MBL2 exon 1 polymorphisms (rs5030737, rs1800450, and rs1800451) on the MBL levels and leprosy immunopathogenesis." (PMID 33013845, 2020).
malaria (13 papers, 2009 to 2023). Malaria is a serious and sometimes fatal disease caused by a parasite that commonly infects a certain type of mosquito which feeds on humans. "Using a non-conditional model, a binary logistic regression, including covariant, anti-malaria drugs, MBL2 gene polymorphism, G6PD and parasitaemia, it was observed that MBL2*AB or AC is protective factor in the development of BWF." (PMID 31941497, 2020). "A study in India reported that the MBL2*LYPA haplotypes confers protection, whereas MBL2*LXPA increases the malaria risk." (PMID 31941497, 2020). "Common MBL2 genetic variants have been associated with various diseases such as filariasis, malaria, leishmaniasis, leprosy, tuberculosis, trypanosomiasis, HIV infection, systemic lupus erythematosus, and rheumatoid arthritis." (PMID 26284055, 2015). "Their role in malaria has been addressed in several studies, and a meta-analysis including four studies suggested an increased risk (odds ratio 1.29, 95% CI 1.08-1.53) for malaria in patients carrying the MBL2*C mutation." (PMID 22380611, 2012). "Frequent polymorphisms found in the MBL2 gene affect the concentration and functionality of the protein and are associated with enhanced susceptibility to severe malaria in African children." (PMID 19432958, 2009). "MBL‐2 polymorphisms were associated with malaria disease severity." (PMID 38099246, 2023). "However, reports from studies conducted on children from a high transmission setting in Gabon and in India show associations of polymorphisms at MBL2 54 with exhibiting symptoms of severe malaria." (PMID 35291755, 2022). "Earlier studies reported the role of MBL2 polymorphism in severe malaria." (PMID 26284055, 2015). "However, contradictory reports have been observed between MBL2 deficiency and malaria." (PMID 35291755, 2022). "Lastly, the preliminary evidence that MBL2 variability in Africa, in particular occurrence of the C allele, is associated with higher Plasmodium falciparum parasite counts and more severe courses of malaria raises the question of TB-malaria counterbalancing effects." (PMID 21695215, 2011). "As such, polymorphisms in G6PD, MBL2, TNF-α, and NOS2 genes in a group of P. falciparum-infected and P. falciparum-uninfected adults and children living in a low and a high malaria transmission setting in Ghana were characterized." (PMID 35291755, 2022). "A recent study in Indian population revealed association between MBL2 LYPA haplotype with protection and MBL2 LXPA haplotype with increased susceptibility to severe malaria." (PMID 26284055, 2015). "The population attributable fraction of severe malaria cases to MBL2*C heterozygosity was estimated to be 17%." (PMID 23533355, 2013). "Among these SNPs, MBL2*C (G57E, rs1800451), the main African MBL variant, which is associated with malaria in children, was present with an allele frequency of 36% in women with placental malaria, and 26% in controls (p = 0.01)." (PMID 22380611, 2012). "MBL2 codon 54 and 57 variants in Gabonese children, LXPA haplotype in Indian population and a novel mutation (−797 C>A) have been linked with susceptibility to severe malaria." (PMID 26284055, 2015). "As MBL forms an active complex with MASP2, the potential interaction between the MBL2 and MASP2 genotypes was also analysed, to evaluate whether specific allele combinations of the two could render the individual susceptible to malaria." (PMID 22380611, 2012). "Prevalence of MBL2 codon 54 heterozygous (AB), minor allele (B) and heterozygous for MBL2 (Y-221X) polymorphism (YX) was higher in severe malaria compared to UM, but these differences could not reach statistically significance levels after Bonferroni correction." (PMID 26284055, 2015). "Common MBL-2 polymorphisms (codon 54, H-550L, and Y-221X) were typed in 336 cases of severe malaria (SM) [94 cerebral malaria (CM), 120 multi-organ dysfunction (MOD), 122 non-cerebral severe malaria (NCSM)] and 131 un-complicated malaria patients (UM)." (PMID 26284055, 2015).
dengue (11 papers, 2012 to 2025). "SNP haplotypes in MBL2 have been significantly associated with dengue severity in Brazilian children with severe dengue when compared to asymptomatic DENV IgG-positive controls." (PMID 38076464, 2023). "In conclusion, our study shows that MBL2 polymorphisms are associated with dengue in a Vietnamese study group and that C2, C4b, C5, C5a and factor D levels are significantly modulated in dengue patients and during the progression of dengue." (PMID 32913345, 2020). "A recent study has also shown an association of MBL2 haplotypes with an increased risk of dengue severity in Brazilians19." (PMID 32913345, 2020). "Results presented here reinforce the association between MBL2 geneand dengue severity among Brazilians." (PMID 31141020, 2019). "A case control study from Brazil has shown the association of wild type alleles of the MBL2 gene with thrombocytopenia in dengue patients." (PMID 22559908, 2012). "Further case control studies are needed to confirm the phenotypic effects of MBL2 gene polymorphisms in dengue patients with primary infection from India." (PMID 22559908, 2012). "In conclusions, MBL2 polymorphisms are associated with dengue in the Vietnamese study population." (PMID 32913345, 2020). "In addition, MBL2 polymorphisms have been shown to be associated with dengue severity in Brazilian and Thai populations." (PMID 32913345, 2020). "However, the association between MBL2 gene and dengue is stillcontroversial and remains to be clearly characterised." (PMID 31141020, 2019). "Even host genetic factors such as genetic variants in FcγRIIa, DC-SIGN, MHC genes, MBL2, CCL-2, TNF-alpha, etc., contribute towards the progression to severe dengue." (PMID 40880375, 2025). "In a matched case–control study conducted in Brazil, the association between MBL2, CLEC5A, ITGB3 and CCR5 genes and dengue severity was investigated in children." (PMID 33766078, 2021). "In dengue and DWS patients, allele MBL2*Y at the promoter region and allele MBL2*A at codons 52 + 54 + 57 significantly contributed to higher MBL levels, whereas alleles MBL2*X and MBL2*O contributed to lower MBL levels (P < 0.05)." (PMID 32913345, 2020). "Other dengue illness severity-related polymorphisms include DC-SIGN (CD209), transporters associated with antigen presentation (TAPs), Fc receptor, cytotoxic lymphocyte antigen 4 (CTLA4), mannose binding lectin-2 (MBL-2) and cytokine genes TNF-α, and TGF-β." (PMID 24623445, 2014).
asthma (10 papers, 2005 to 2025). "Higher levels of circulating MBL protein were related to baker’s asthma, as well as specific polymorphisms in MBL2 gene." (PMID 40077585, 2025). "Deficiencies in this gene have been associated with susceptibility to autoimmune and infectious diseases, and a well-defined but weak association has been found between some SNPs of MBL2 and asthma and atopy in children." (PMID 25326706, 2014). "Moreover, an association was shown between an allelic variant of MBL2 gene leading to decreased MBL concentration in serum and higher risk of asthma in children presenting with recurrent and chronic Chlamydia pneumonia infection." (PMID 21918651, 2012). "However, MBL2 gene polymorphisms have been reported not to be associated with the atopy status and asthma phenotype in adults." (PMID 37996869, 2023).
breast carcinoma (10 papers, 2010 to 2024). "Genetic variants of MBL2 are associated with the progression of ovarian, gastric, lung, and breast cancer." (PMID 37835594, 2023). "To date, five studies have examined the association between MBL2 polymorphisms and risk of cancer, including breast cancer, stomach cancer, colon cancer and cervical cancer." (PMID 23637788, 2013). "Genetic variants in the 3′-UTR of MBL2 could potentially influence the risk of breast cancer in African American women." (PMID 37835594, 2023). "In addition, the polymorphism of MBL2 might have influence on the risk of breast cancer in African-American women." (PMID 20587030, 2010). "Introduction of Abmb into the blood circulation might compensate downregulation of MBL2, slow down breast cancer cell growth, and stimulate the immune system." (PMID 32443732, 2020). "CD95 and MBL2, two immune function genes, the promoter single nucleotide polymorphisms (SNPs) of CD95 (rs2234767) and MBL2 (rs7096206) are associated with grade 3 infection following treatment of breast cancer with cytotoxic therapy." (PMID 28085094, 2017). "Similar associations were also noted between MBL2 haplotypes and breast cancer risk among African-American women, but not Caucasians." (PMID 23637788, 2013). "The MBL2 SNP identified in that study as being associated with AMD severity has neither been shown to influence serum MBL levels nor associate with other diseases such as colon cancer or breast cancer." (PMID 26207622, 2015). "Interestingly, breast cancer chemotherapy using the combination of doxorubicin and cyclophosphamide is reported to have a negative impact because the mannose-binding lectin 2 (MBL2) expression in breast cancer patients receiving this combination of drugs is downregulated." (PMID 32443732, 2020).